MYB (MYB proto-oncogene, transcription factor)
Diseases named in the same sentence as MYB in open-access papers (continued):
Sharing a sentence is not in itself a finding about the gene and the disease.
atrial fibrillation (1 paper, 2021). A disorder characterized by an electrocardiographic finding of a supraventricular arrhythmia characterized by the replacement of consistent P waves by rapid oscillations or fibrillatory waves that vary in size, shape and timing and are accompanied by an irregular ventricular response. "In this study, based on dataset GSE41177, we found that the expression levels of MYB in 16 left atria junctions of patients with atrial fibrillation were significantly upregulated (FC = 1.58, P = 5.48562E − 07) compared with a normal person." (PMID 34938350, 2021). "Subsequently, MYB expression is identified to significantly upregulate in atrial fibrillation based on dataset GSE41177." (PMID 34938350, 2021). "In conclusion, our data find that circFAT1(e2) sponges miR-298 and then regulates MYB expression, thus affecting atrial fibrillation progression." (PMID 34938350, 2021). "Subsequently, based on the GSE41177 dataset, we identified 1982 differentially expressed genes (DEGs) in atrial fibrillation, and all DEGs were upregulated, including MYB." (PMID 34938350, 2021).
autoimmune disease (1 paper, 2019). A disorder resulting from loss of function or tissue destruction of an organ or multiple organs, arising from humoral or cellular immune responses of the individual to their own tissue constituents. "MYB is also characterized as an early regulator of T-cell associated diseases with an altered expression in autoimmune diseases." (PMID 30984166, 2019). "Of interest, MYB is known to be required for regulatory T cell homeostasis in periphery as MYB deletion in these cells resulted in the development of multi-organ autoimmune diseases." (PMID 30984166, 2019).
Autoimmunity (1 paper, 2025). The occurrence of an immune reaction against the organism's own cells or tissues. "Our study further reveals that transcriptional regulators such as IRF3, IRF7, STAT1, and MYB are critically involved in T cell-mediated autoimmunity, along with ncRNAs LINC00487, LINC01260, and MIR223 with their expression patterns linked to immune dysregulation." (PMID 39844998, 2025). "•MYB acts as a key regulator in T cell activation, promoting autoimmunity in SLE." (PMID 39844998, 2025).
benign prostatic hyperplasia (1 paper, 2023). A non-cancerous nodular enlargement of the prostate gland. "In this study, we have examined the expression of MYB in malignant prostate and adjacent benign prostatic hyperplasia (BPH) and high-grade prostate intraepithelial neoplastic (HGPIN) lesions from Black and White patients." (PMID 38089573, 2023).
bladder tumor (1 paper, 2017). "At the opposite, others markers of IGFR inhibitor sensitivity identified previously such as MYB did not predict sensitivity to AEW541 in bladder tumor derived cell lines and seem so to be cancer specific (data not shown)." (PMID 28882129, 2017).
breast lobular carcinoma (1 paper, 2019). An adenocarcinoma of the breast arising from the lobules. "CD68 was inversely correlated with MYB in breast lobular carcinomas (r = −0.282, p < 0.001, n = 83), only marginal associations were found in ductal and other carcinomas." (PMID 31406165, 2019).
clear-cell carcinoma (1 paper, 2021). "Among the different histological subtypes, the highest incidence of MYB positivity was recorded in serous carcinoma (97%, 249/256) and mucinous carcinoma (97%, 36/37), followed by clear-cell carcinoma (83%, 10/12), and endometrioid carcinoma (75%, 9/12)." (PMID 34145334, 2021).
cortical dysplasia (1 paper, 2025). "Interestingly, LEATs other than PLNTY, including ganglioglioma, DNET, and MYB- or MYBL1-altered pLGGs, also frequently coexist with regional cortical dysplasia." (PMID 40668344, 2025).
endometrial tumors (1 paper, 2022). "In NGS, the microsatellite (MS) loci, including EWS RNA-binding protein 1, paired box 8, and MYB, also showed instability in endometrial tumors." (PMID 36142641, 2022).
endometriosis (1 paper, 2020). The growth of functional endometrial tissue in anatomic sites outside the uterine body. "miR-200b-3p was associated with the transcription factors DNMT1, EZH2, HNF1B, JUN, MYB, ZEB1, and ZEB2 during the pathogenesis of endometriosis." (PMID 32802844, 2020). "Then, DNMT1, EZH2, HNF1B, JUN, MYB, ZEB1, and ZEB2 were found as TFs related to endometriosis by interacting with target genes of miR-200b-3p." (PMID 32802844, 2020).
essential thrombocythemia (1 paper, 2015). A chronic myeloproliferative neoplasm that involves primarily the megakaryocytic lineage. "The SNP between HBS1L and MYB, rs9376092, has a stronger effect in JAK2V617F-negative cases with somatic CALR and/or MPL mutations and predisposes to essential thrombocythemia in JAK2V617F-positive cases." (PMID 25849990, 2015).
Fusarium infection (1 paper, 2021). "The results also showed that TF families that were involved include MYB, MYB-related, AP2-EREBP, bHLH, WRKY, and NAC suggesting that these TF play important roles in response to Fusarium infection of banana." (PMID 33809411, 2021).
head and neck squamous cell carcinoma (1 paper, 2023). A squamous cell carcinoma that arises from any of the following anatomic sites: lip and oral cavity, nasal cavity, paranasal sinuses, pharynx, larynx, and salivary glands. "However, our data from GTEx and TCGA databases indicated that MYB expression is significantly lower in head and neck squamous cell carcinoma and lower expression of MYB predicts poorer prognosis, suggesting that MYB acted as a tumor suppresser in head and neck squamous cell carcinoma." (PMID 36994664, 2023).
Hyperkeratosis (1 paper, 2023). Hyperkeratosis is a histopathological term defining a thickened stratum corneum and may be present in many different skin conditions, with many possible overlaps. "We speculate that KRT17 is upregulated under high glucose and promotes keratinocyte proliferation and migration caused hyperkeratosis, through the c-MYB/PI3K-AKT pathway, contributing to delayed wound healing." (PMID 37929023, 2023).
invasive breast carcinoma (1 paper, 2024). A carcinoma that infiltrates the breast parenchyma. "Notably, 16 non-adenoid cystic TNBCs demonstrated variable expression of MYB (all of them in less than 25% of tumor cells); the majority of these were categorized as invasive breast carcinomas of no special type (88%, 14 of 16)." (PMID 37306115, 2024).
iron overload (1 paper, 2021). "Furthermore, the rs9399136[C] variant at the HBS1L/MYB locus is protective against IDA while increasing the risk of iron overload." (PMID 33536631, 2021). "The rs9399136[C] variant in the intergenic HBS1L/MYB region is the only variant to associate with both IDA (OR = 0.84 [0.80–0.89], P = 4.7 × 10−11) and iron overload (OR = 1.13 [1.07–1.20], P = 1.4 × 10−5)." (PMID 33536631, 2021).
ischemia (1 paper, 2021). A hypoperfusion of the BLOOD through an organ or tissue caused by a PATHOLOGIC CONSTRICTION or obstruction of its BLOOD VESSELS, or an absence of BLOOD CIRCULATION. "Since VEGF possesses a paramount role in cerebral angiogenesis after ischemia, whether the change in MYB expression has an influence on VEGF needs to be further explored." (PMID 33815136, 2021).
lung mucoepidermoid carcinoma (1 paper, 2020). "As AcCC cell lines are not available, we utilized NCI-H292 cells, a lung mucoepidermoid carcinoma cell line (MEC) that expresses very low levels of NR4A3 and MYB, making it a suitable model to interrogate functional interactions between the NR4A3 and Myb proteins." (PMID 32867110, 2020).
lymph node metastasis (1 paper, 2025). "The chi-square test and Fisher’s exact test indicated that postoperative RCB classification demonstrated a statistically significant correlation with the expression levels of UGCG, BTG2, TNFRSF21, and MYB, as well as lymph node metastasis in BRCA patients prior to NAC." (PMID 40332226, 2025). "A subsequent investigation of associations demonstrated that UGCG and TNFRSF21 expression levels showed a positive relationship with NAC, whereas the expression of BTG2 and MYB, as well as the lymph node metastasis, were negatively correlated with the efficacy of NAC." (PMID 40332226, 2025). "Specifically, patients were more likely to achieve a higher RCB classification when they were negative for UGCG and TNFRSF21, but positive for BTG2 and MYB, with no lymph node metastasis." (PMID 40332226, 2025).
lymphoid leukemia (1 paper, 2023). A malignant lymphocytic neoplasm of B-cell or T-cell lineage involving primarily the bone marrow and the peripheral blood. "Here, we identified HDACi as potent inhibitors of MYB gene expression also in lymphoid leukemia cells, suggesting a conserved mechanism of MYB gene regulation in neoplasms of both the myeloid and lymphoid lineages." (PMID 37077825, 2023).
metastasis (1 paper, 2022). The spread or migration of cancer cells from one part of the body (where they first appeared) to another. "In these two visceral metastasis cases, positive expression of MYB was found in both breast and primary lung metastases." (PMID 35590093, 2022). "However, the patient with liver metastasis was negative for MYB protein and gene rearrangement in both the primary and metastatic sites." (PMID 35590093, 2022).
mucinous carcinoma (1 paper, 2021). "MYB was overexpressed in all major epithelial OC histological subtypes exhibiting the highest incidence (~ 97%) and overall expression in serous and mucinous carcinomas." (PMID 34145334, 2021).
ovarian tumors (1 paper, 2021). "Overall, we observed a positive association of MYB expression (mean composite score) with the increasing histological grade of ovarian tumors." (PMID 34145334, 2021). "To analyze MYB expression in OC, we performed immunohistochemical analysis on tissue sections from the normal ovary (n = 23) and ovarian tumors (n = 373)." (PMID 34145334, 2021).
pancreatic adenocarcinoma (1 paper, 2016). "In MYB-silenced cells, the pancreatic adenocarcinoma signaling was also negatively regulated due to the inhibition of EGFR and NF-κB." (PMID 27354262, 2016).
prostate (1 paper, 2023). "Since MYB dysregulation starts early and increases progressively, it is liked involved in early and late events of prostate carcinogenesis." (PMID 38089573, 2023). "Aberrant MYB expression was also noticeable in HGPIN suggesting that its dysregulation starts early and may be involved in initial stages of prostate carcinogenesis." (PMID 38089573, 2023).
prostate intraepithelial neoplasia (1 paper, 2022). A neoplastic proliferation of the epithelial cells that line the acini and the ducts of the prostate gland. "It is noted that apigenin does not drive the formation of prostate intraepithelial neoplasia and suppresses MYB to indirectly reduce the mobility of cancer cells, to avoid metastasis and cell proliferation for lean PCa." (PMID 35164166, 2022).
renal oncocytomas (1 paper, 2019). "In the KORT database, around 32% of samples showed low MYBBP1A expression, high PGC1α expression, and high expression of c‐MYB target genes, all of these samples being chRCCs or renal oncocytomas." (PMID 31066170, 2019).
salivary gland adenoid cystic carcinoma (1 paper, 2023). An adenoid cystic carcinoma arising from the salivary gland. "MYB-NFIB fusion and NOTCH1 mutation are common hallmark genetic events in salivary gland adenoid cystic carcinoma (SACC)." (PMID 36879115, 2023).
thymoma (1 paper, 2022). A neoplasm arising from the epithelial cells of the thymus.
tumor (264 papers, 1991 to 2026). "In fact, studies have highlighted a potential role for the MYB in terms of regulating cell cycle progression, thus causing rapid tumor growth." (PMID 38315329, 2024). "GT3-INCP/GATA3 bound to common cis regulatory elements and upregulated the expression of the tumor-promoting and estrogen-regulated BC susceptibility/risk genes MYB and PDZK1." (PMID 36856111, 2023). "The functional consequence of this fusion is the loss of the tumor suppressor function of QKI combined with the activation of MYB." (PMID 37920791, 2023). "In order to further identify the association between MYB and tumor immune environment, we calculated the immune infiltration score and explored the immune cell infiltration." (PMID 36994664, 2023). "At the same time, low-expression level of MYB was detected in FAP (+) tumor-associated fibroblasts by microarray." (PMID 36994664, 2023). "Comparing with the different cluster, more malignant cells were found in Inter-Duct 3, which activated tumor-associated signaling pathways by upstream TFs, MYB and EN1." (PMID 36465348, 2022). "This study also demonstrated that MYB-QKI fusion was able to drive tumorigenesis via simultaneous activation of MYB as a result of enhancer translocation combined with the loss of the tumor suppressor activity of QKI." (PMID 36699536, 2022). "Since MYB expression exhibited a positive association with increasing tumor grade and stage, we next examined if MYB levels correlated with the survival of OC patients by performing Kaplan–Meier analysis." (PMID 34145334, 2021). "Despite the mutations in MYB oncoproteins being reported frequently in numerous cancers, the precise mechanisms of tumour initiations and/or maintenance remains vague." (PMID 34921182, 2021). "As a second approach we used patient-derived ACC cells that represents a second type of MYB-dependent neoplasm that is associated with the expression of oncogenic MYB-NFIB fusion proteins due to MYB and NFIB gene fusions." (PMID 35008207, 2021). "Among these upregulated PRC2+-CGI genes, we found many well-defined oncogenes and genes encoding tumor-promoting factors such as MYB, TWIST1, SYK, TEAD4, FOXC1, and FGFR3." (PMID 33931649, 2021). "Overexpression of MMP8 is significantly associated with higher clinical stage, overexpression of MMP11 is significantly associated with bigger tumor size, and low expression of MYB is significantly related to worse pathologic grade and metastasis." (PMID 32309437, 2020). "These targeted MYB-NFIB variants were only present in ACC tumours that exhibited strong MYB 5′/MYB 3′ gene expression imbalances." (PMID 31301736, 2019). "In the case of ACC 22, sequencing not only confirmed MYB-NFIB variant 2 but also showed the additional robust presence of a MYB exon 16-NFIB exon 12 fusion transcript confirming the expression of at least one additional MYB fusion variant in this tumour." (PMID 31301736, 2019). "Alternatively, RNA-based assays such as RT-PCR, are able to better characterize ACC by not only confirming the expression of MYB-NFIB transcripts but by also providing information regarding the fusion variants present in a tumour." (PMID 31301736, 2019). "The fact that each downstream mutation from MYB-NFIB is relatively rare across various ACC tumors further reinforces the critical need for individualized tumor phenotyping." (PMID 26359351, 2015). "To tumor heterogeneity, we focused on tumorigenic cell populations, profiled plasma and T cell enrichment within the tumor microenvironment and identified key pathways and transcriptional drivers including the MYB-NFIB fusion underlying the tumor cluster formation." (PMID 40950184, 2025). "Additionally, cell clusters with high MYB expression also exhibit elevated expression of multiple genes associated with tumor invasion and metastasis, particularly NTRK3, which encodes a member of the neurotrophic tyrosine receptor kinase family." (PMID 39263605, 2024).
tumor (continued). "Transactivation of BUB1 by MYB may promote tumour development, since overexpression of BUB1 cause hyper‐activation of Aurora B activity, aneuploidy, and spontaneous and MYC‐induced transformation in a transgenic mouse model." (PMID 38112379, 2024). "Therefore, proteins such as MYB or A-MYB, triggered by C-terminal truncations, can cause a unique tumor phenotype of ACC." (PMID 38966479, 2024). "This contradiction may largely be caused by tumor heterogeneity, implying that the spatiotemporal specify of MYB RNA may decide and lead to diverse cell fate in tumor genesis and progression." (PMID 36994664, 2023). "A positive association of MYB with increasing tumor grade and stage may result from its involvement in epithelial-mesenchymal transition and gain of aggressive phenotypic traits." (PMID 38089573, 2023). "Our team aimed to exhibit the association between MYB and tumor progression and TIME for determining whether MYB could serve as a biomarker for cancer screening, prognosis and accurate therapy design." (PMID 36994664, 2023). "However, an increasing number of studies have suggested that MYB can affect the complexity of cancer progression by regulating tumor-associated noncoding RNAs (ncRNAs), such as microRNAs, long-non-coding RNAs and circular RNAs." (PMID 34876130, 2021). "To further understand the molecular mechanisms underlying the anti-tumor effect of LOC102724169 in modulating MYB, we found that the PI3K/AKT pathway was the most enriched pathway through KEGG pathway enrichment analysis of high-throughput sequences; MYB was dysregulated in this pathway." (PMID 33850634, 2021). "Deletion of the MYB regulatory C-terminal domain may be a driving mutation leading to tumorigenesis, therefore, different tumor mechanisms produce similar MYB proteins." (PMID 34876130, 2021). "Hence, MYBBP1A loss will occur in a tumor with expression of c-MYB and will have functionality by increasing c-MYB activity." (PMID 30781655, 2019). "We have proposed that the restoration of proliferation required for a secondary tumor to form may be linked to the reversion of EMT, or MET, and we suggest that MYB plays a central role here in promoting tumor growth and the epithelial phenotype." (PMID 24283570, 2013). "The results proved that MYB expression showed significant difference among several immune subtypes and molecular subtypes in most cancers, which could demonstrate that MYB is a valuable pan-cancer diagnostic biomarker and involved in the tumor immune environment regulation." (PMID 36994664, 2023). "However, it is unclarified whether MYB affects different tumor immune microenvironments and the pathogenic role of MYB in various cancer types still remains unclear." (PMID 36994664, 2023). "Besides its role in normal cells, MYB (protein) has been implicated in human neoplasia." (PMID 35008207, 2021). "The poor prognosis of this tumor may be associated with MYB expression." (PMID 32695659, 2020). "However, MYB amplification was significantly associated with tumor stage (FDR = 0.03)." (PMID 28426752, 2017). "Although the tumor-suppressive properties of miRNA-195-5p have been acknowledged, the precise pathways through which it exerts its effects, particularly concerning MYB and the PI3K/AKT/mTOR signaling cascade, remain inadequately investigated." (PMID 41141380, 2025). "Conversely, the genes downregulated in the MYB-expressing epithelial clusters were predominantly tumor-suppressive transcriptional signatures, including OCM, IER2, JPH2, RYR3, MYH11and B3GALT1." (PMID 40950184, 2025). "Rescue experiments confirmed the functional reciprocity, wherein MYB overexpression reversed the tumor-suppressive effects of miRNA-195-5p and reactivated PI3K/AKT/mTOR signaling, mirroring the clinical scenario of pathway activation during resistance." (PMID 41141380, 2025).